KCNJ5 (potassium inwardly rectifying channel subfamily J member 5)
Diseases named in the same sentence as KCNJ5 in open-access papers (continued):
Sharing a sentence is not in itself a finding about the gene and the disease.
left ventricular hypertrophy (4 papers, 2017 to 2022). Enlargement of the LEFT VENTRICLE of the heart. "In our previous study, APA patients with KCNJ5 somatic mutations had a higher degree of left ventricular hypertrophy and worse diastolic function." (PMID 35311227, 2022). "A subsequent large prospective cohort study using propensity score matching showed that surgery in the cases with APA harboring KCNJ5 mutation group significantly improved left ventricular hypertrophy compared to the KCNJ5 wild group." (PMID 36012306, 2022). "Although increases in left ventricular mass index (LVMI) and left ventricular hypertrophy (LVH) has been detected in KCNJ5-mutant carriers, evidence evaluating the outcome of vascular status in those with KCNJ5 somatic mutations after adrenalectomy was insufficient." (PMID 28415786, 2017). "Interestingly, in this study, when the outcome was left ventricular diastolic function, measured through a functional assessment of left ventricular hypertrophy, the benefit of adrenalectomy was seen only in the KCNJ5 mutant group and not in the KCNJ5 wild type group." (PMID 36012306, 2022).
Bradycardia (3 papers, 2018 to 2023). A slower than normal heart rate (in adults, slower than 60 beats per minute). "As set out in the introduction, the W101C KCNJ5 variant is associated with bradycardia." (PMID 37894977, 2023).
adrenal carcinoma (2 papers, 2016 to 2022). A carcinoma involving a adrenal gland. "Steroid metabolomic analysis of cultured cells with the KCNJ5 mutation was performed and compared with that of the human adrenal carcinoma cell line (HAC15) without the KCNJ5 mutation." (PMID 35207229, 2022).
Brugada syndrome (2 papers, 2022 to 2025). A genetically heterogeneous condition characterized by complete or incomplete right bundle branch block accompanied by ST elevation in leads V1-V3. "The previous studies also found a variant on the KCNJ5 (potassium voltage-gated channel subfamily E regulatory subunit 5) gene located on chromosome X in Japanese patients with Brugada syndrome." (PMID 36617651, 2022).
channelopathies (2 papers, 2015 to 2022). "The variations in phenotypes resulted from different mutations in KCNJ5 also have implications for the potential channelopathy of PA15." (PMID 26066391, 2015). "Heterozygous mutations in the conservative filter of KCNJ5 at p.Gly151Arg were the most common channelopathy in our cohort." (PMID 26066391, 2015).
chronic kidney disease (2 papers, 2022 to 2024). Impairment of the renal function secondary to chronic kidney damage persisting for three or more months. "KCNJ5 mutation exhibits a protective effect against the risk of chronic kidney disease after unilateral adrenalectomy." (PMID 39574955, 2024). "KCNJ5 wild-type status was significantly correlated with the occurrence of chronic kidney disease after adrenalectomy." (PMID 39574955, 2024).
hyperplasia (2 papers, 2015 to 2022). An abnormal increase in the number of cells in an organ or a tissue with consequent enlargement. "Somatic KCNJ5 mutations were detected in 17 (65.4%) of the 26 APA cases, but no mutations were detected in one hyperplasia case." (PMID 35444613, 2022).
pheochromocytoma (2 papers, 2021 to 2024). "Also, similar to pheochromocytoma, in APA miRNA signature was also reflected in germline mutation carrier status, and miR-299 from locus 14q32 was found downregulated in KCNJ5 mutant APA vs. non-KCNJ5 mutant samples." (PMID 34066712, 2021).
Sinus bradycardia (2 papers, 2020 to 2023). Bradycardia related to a mean resting sinus rate of less than 50 beats per minute. "Here, the pathogenic mechanism of the W101C KCNJ5 mutation underlying sinus bradycardia in a patient-derived cellular disease model of sinus node dysfunction (SND) was investigated." (PMID 37894977, 2023).
adrenocortical carcinomas (1 paper, 2012). "KCNJ5 mutation (L168R) was also found in one of three aldosterone-secreting adrenocortical carcinomas (33%)." (PMID 22848660, 2012). "In addition, one KCNJ5 mutation was found in an aldosterone-secreting adrenocortical carcinoma." (PMID 22848660, 2012).
aldosteronoma (1 paper, 2022). "Aldosteronomas are a major cause of unilateral PA, associated with somatic variants in KCNJ5, CACNA1D, ATP1A1, ATP2B3, CLCN2, CACNA1H and CTNNB1 genes." (PMID 35813615, 2022). "KCNJ5 mutational status and classical histopathology of unilateral PA (aldosteronoma) have emerged as relevant predictors of clinical and biochemical outcome, respectively." (PMID 35813615, 2022). "In a Brazilian cohort of PA, complete clinical success based in PASO criteria was more frequent in patients with aldosteronomas harboring KCNJ5 pathogenic variants than in those with pathogenic variants in other driver genes." (PMID 35813615, 2022). "KCNJ5 somatic variants are predominant among aldosteronomas (classical histology), whereas CACNA1D is the most frequent mutated gene in APMs." (PMID 35813615, 2022). "Interestingly, KCNJ5 pathogenic variants have been more frequently detected in aldosteronomas (classical histopathology), which is associated with a higher chance of postsurgical complete biochemical success." (PMID 35813615, 2022). "Interestingly, KCNJ5 mutational status and classical histopathology of unilateral PA (aldosteronoma) have emerged as relevant predictors of clinical and biochemical outcome, respectively." (PMID 35813615, 2022). "In 2013 after KCNJ5 discovery, somatic CACNA1D gain-of-function variants were reported in aldosteronomas, with a prevalence of around 10%." (PMID 35813615, 2022). "In contrast with KCNJ5 related aldosteronomas, CACNA1D tumors are significantly smaller and more frequent in older male patients." (PMID 35813615, 2022). "Characteristically, KCNJ5 mutant aldosteronomas are more frequent in female (>70%) and younger patients, with larger tumor size." (PMID 35813615, 2022). "KCNJ5 is the most frequently affected gene in aldosteronomas (>40%), with even higher prevalence in Japanese and/or Eastern Asian cohorts (65-69% approximately)." (PMID 35813615, 2022).
aortic atherosclerosis (1 paper, 2022). A atherosclerosis that involves the aorta. "However, we focused on the influence of KCNJ5 mutations with regards to aortic atherosclerosis in this study; therefore, our conclusions may not be affected by the lack of IHC-guided biopsy." (PMID 35311227, 2022).
epilepsy (1 paper, 2021). A brain disorder characterized by episodes of abnormally increased neuronal discharge resulting in transient episodes of sensory or motor neurological dysfunction, or psychic dysfunction. "Additionally, a number of VGKCs including KCNB2, KCNF1, KCNK6, KCNK9 and KCNJ5 are significantly upregulated in the NRXN1α+/- transcriptome, and gain of function of VGKCs has been identified in neurodevelopmental disorders including epilepsy." (PMID 34525970, 2021).
Hyperkalemia (1 paper, 2024). An abnormally increased potassium concentration in the blood. "Additionally, the percentage of patients with postoperative hyperkalemia was also higher in patients with KCNJ5-WT than in patients with KCNJ5 mutation." (PMID 39574955, 2024).
myopia (1 paper, 2023). "We examined the top 64 myopia-associated loci that were expressed in the retinal layers and associated with common refractive errors, SNPs representing TSPAN10, KCNJ5, TFAP2B, and FBN2 had |nSL|> 2, which were under strong selection." (PMID 37919796, 2023).
pathological myopia (1 paper, 2019). Excessive axial myopia associated with complications (especially posterior staphyloma and CHOROIDAL NEOVASCULARIZATION) that can lead to BLINDNESS. "The KCNJ5 gene is considered a candidate SNP variation for increased risk of pathological myopia in genome-wide association analysis studies." (PMID 31839753, 2019).
tumor (31 papers, 2012 to 2025). "Individuals with positive immunostaining for CYP11B1 correlated with wild-type KCNJ5 (p = 0.018), respective CYP11B2 positive was more often found in tumours with KCNJ5 mutation (p = 0.007)." (PMID 36428832, 2022). "A meta-analysis showed that APA patients with KCNJ5 mutation have phenotypic features of higher plasma aldosterone levels, young age, female sex, and larger tumor size." (PMID 33920271, 2021). "Of note, HSD3B1 immunoreactivity was correlated with CYP11B2 in the tumor area, and higher mRNA levels in KCNJ5-mutated APAs than wild type." (PMID 33802814, 2021). "Adrenal glands with tumor harboring KCNJ5 mutation had higher NP-59 uptake than contralateral adrenal glands both by direct comparison (CON) and corrected by liver background (ALR)." (PMID 33995277, 2021). "In particular, KCNJ5-mutated APAs frequently represent large tumors and are composed of abundant clear tumor cells." (PMID 33802814, 2021). "We defined three mutational subgroups: KCNJ5-mutated tumours, ATPase-mutated tumours and CTNNB1-mutated tumours." (PMID 31000732, 2019). "None of the genes in either of the analyses were differentially expressed in KCNJ5- or ATPase-mutated tumours." (PMID 31000732, 2019). "When CTNNB1-mutated tumours were excluded, 40 genes were found differentially expressed between tumours with KCNJ5 mutations and tumours with ATPase or CACNA1D mutations." (PMID 31000732, 2019). "Nevertheless, these results are concordant with previous suggestions that KCNJ5-mutated tumours co-secrete cortisol and aldosterone." (PMID 31000732, 2019). "One study identified higher expression of the zona glomerulosa-associated gene NPNT in ATPase-/CACNA1D -mutated tumours compared to KCNJ5-mutated tumours." (PMID 31000732, 2019). "Of these, 13 were higher expressed in KCNJ5-mutated tumours and 27 had higher expression in the ATPase/CACNA1D group." (PMID 31000732, 2019). "The investigated CTNNB1 mutated APA lysates (n = 3) contained aldosterone at similar levels as KCNJ5 mutated tumor lysates (p = 0.48)." (PMID 26815163, 2016). "APAs harboring KCNJ5 mutations may have a more disorganized process of tumor cell differentiation and formation than APAs with ATPase or CACNA1D mutations." (PMID 36012306, 2022). "In addition, previous work demonstrated that enhanced glycolysis can combat oxidative stress via increasing glutathione metabolism and maintaining redox balance, a potential factor contributing to the larger tumor diameter in APAs with KCNJ5 mutations." (PMID 34359615, 2021). "KCNJ5 is the most frequent genetic mutations in APAs with overall prevalence of 43%, ranging from 12% to 80% and it is widely studied for the correlation with phenotype, mainly in female, with younger age, larger tumor and higher PAC." (PMID 33995277, 2021). "In the fifteen tumours subjected to RNA-Sequencing in this study, opposite patterns of expression in tumours with mutations in KCNJ5 and those with mutations in CACNA1D/ATP1A1/ATP2B3 were observed, with KCNJ5-mutants showing higher levels of CYP11B1 expression and lower levels of CYP11B2 expression." (PMID 31000732, 2019). "Altered sodium permeability due to KCNJ5 (encoding Kir3.4) mutations results in cellular depolarization and increased intracytoplasmic calcium levels via voltage-gated calcium channels in affected tumor cells." (PMID 29594118, 2018). "Whether this gender bias for KCNJ5 mutation is attributable to a difference in the rate at which these mutations occur in females vs. males or to differences in the likelihood of tumor development following mutation will be of interest to determine." (PMID 22848660, 2012). "Three were canonical oncogene drivers, namely HOXC11, SOX2, and KCNJ5, while the rest 25 are putative oncogenes and putative tumor suppressors in almost equal measure." (PMID 39484215, 2024). "Somatic mutations in KCNJ5, ATP1A1, ATP2B3, CACNA1D and CTNNB1 have been described in ~60% of these tumours." (PMID 31000732, 2019).
tumor (continued). "Asian patients with KCNJ5 somatic mutations have similar characteristics but without differences in sex and tumor size compared to patients without KCNJ5 somatic mutations." (PMID 36950676, 2023). "In contrast, this is not a feature of APAs with a KCNJ5 mutation which are characterized by their larger tumor size." (PMID 36004349, 2022). "Unrestrained proliferation of adrenal cells carrying a KCNJ5 mutation contrasts with specific gene expression programs elicited in KCNJ5 mutation negative APAs which influence adrenal cell viability and potentially regulate tumor size." (PMID 36004349, 2022). "However, several other clinical characteristics of APA patients with KCNJ5 mutations have been reported: younger age, female dominant, lower potassium level, higher aldosterone value, and large tumor size compared to KCNJ5 wild APA cases." (PMID 36012306, 2022). "If a visible tumor is predicted to have KCNJ5 mutation, adrenalectomy is recommended without AVS for the prevention of cardiovascular complications and better prognosis." (PMID 36012306, 2022). "If the tumor does not carry the KCNJ5 mutation, AVS should be recommended to those who receive surgical benefit." (PMID 36012306, 2022). "In contrast, only 106 genes were differentially expressed between tumours carrying KCNJ5-mutations and those without KCNJ5-mutations, and 75 genes between tumours with ATPase mutations and those without." (PMID 31000732, 2019). "Analysis of a larger sample set of tumours showed that VSNL1 was overexpressed in APAs carrying a KCNJ5 mutation compared with those APA without a KCNJ5 mutation." (PMID 29642543, 2018). "The significant differences between KCNJ5 mutant and wild-type tumors initiated a scientific discussion on the possibility that tumor formation and hyperfunctionality may represent independent processes." (PMID 29594118, 2018). "Similarly, the specific KCNJ5 mutations likely result in specific alterations in channel structure that might allow selective inhibition of mutant channels, which would be expected to inhibit aldosterone secretion and arrest progression of tumor growth in affected patients." (PMID 22848660, 2012). "However, later studies reported distinct expression profiles of APA with KCNJ5 mutations compared with APA without KCNJ5 mutations (with higher CYP11B2 expression in the tumours with KCNJ5 mutations)." (PMID 29642543, 2018). "Moreover, KCNJ5-mutated tumor tissue showed a higher number of large clear cells than nonmutant tumor tissue." (PMID 29770148, 2018). "The majority of studies documenting the KCNJ5 genotype of APAs reported that patients harboring a KCNJ5 mutant APA were more commonly females, adrenalectomized at a younger age, with a larger tumor size than those harboring a KCNJ5 wild-type APA." (PMID 31636604, 2019). "Utilizing this technique, we sequenced DNA from the CYP11B2 positive tumor and CYP11B2 negative adjacent normal tissue and demonstrated the presence of somatic KCNJ5 mutation p.I157S in the tumor and not the adjacent normal area." (PMID 36051386, 2022). "The aldosterone-producing tumours and ACS have a higher rate of not harbouring KCNJ5, but KCNJ5 gene mutations have been described in ACS-PA, too." (PMID 36428832, 2022). "The frequency of ATP1A1 mutation determined through Sanger sequencing performed on whole tumor sample DNA was not as high as that of KCNJ5 reported previously." (PMID 33920271, 2021). "Altogether the findings suggest that perhaps undergoing adrenalectomy at a younger age and having a larger tumor size is reflective of patients' gender rather than the KCNJ5 genotype of the APA." (PMID 31636604, 2019). "Thus, Connshing syndrome seems more frequent in aldosteronomas with negative KCNJ5 and larger tumours, being correlated with a reduced rate of clinical success (36.8%)." (PMID 36428832, 2022).
cancer (5 papers, 2005 to 2022). A tumor composed of atypical neoplastic, often pleomorphic cells that invade other tissues. "Furthermore, KCNJ5 mutated APAs that have a higher proliferative index display increased expression of genes involved in glycolysis and lipid metabolism, an observation reminiscent of the well-characterized role of metabolic reprogramming in cancer progression." (PMID 34771744, 2021).
metabolic disorders (3 papers, 2023 to 2024). "KCNJ5 mutation is also associated with changes in cardiac structure, function and metabolic disorders in patients with PA." (PMID 38965078, 2024). "Investigations of the impacts of KCNJ5 mutations on symptoms, prognosis, and even systemic target organ damage, including cardiovascular structure and function, and metabolic disorders, may affect the treatment strategy of patients." (PMID 36950676, 2023).
cardiovascular disease (1 paper, 2023). "Great complexity arises when trying to discern the role of KCNJ5 in cardiovascular disease." (PMID 37446026, 2023). "Given that GIRK4 is primarily expressed in atrial myocytes, iPSCs can be used to study the role of KCNJ5 in cardiovascular disease." (PMID 37446026, 2023).
KCNJ5 also shares sentences with these, for which no sentence is quoted: essential hypertension (4 papers); Adrenocortical Tumor (3); cardiac arrhythmia (3); secondary hypertension (3); Abdominal obesity (2); cardiac diseases (2); cardiomyopathy (2); Familial hyperaldosteronism type I (2); sick sinus syndrome (2); Alzheimer disease (1); Andersen-Tawil syndrome (1); atrial tachycardia (1); autism (1); Autoimmunity (1); AV block (1); B-cell lymphomas (1); breast tumors (1); Cushing syndrome (1); deafness (1); dilated cardiomyopathy (1); endothelial dysfunction (1); Familial adenomatous polyposis (1); gastric carcinoma (1); heart defects (1); heart failure (1); Hypoinsulinemia (1); ischemia (1); leukemia (1); lung carcinoma (1); lymphoma (1).
A further 17 diseases each share a sentence with KCNJ5 in 1 paper.